INS (insulin)
Diseases named in the same sentence as INS in open-access papers (continued):
Sharing a sentence is not in itself a finding about the gene and the disease.
diabetes (continued). "Diabetic mice showed higher Cavβ3 (a voltage-gated Ca2+ channel subunit) expression, coupled with impaired calcium signaling and insulin secretion, and these effects were reduced in high-fat diet-induced diabetes in Cavβ3 deficient mice." (PMID 37371672, 2023). "We evaluated incident type 2 diabetes, insulin requirements, and diabetes-associated complications during a 10-year follow-up period using the log-rank test and Cox proportional hazards regression models." (PMID 36831436, 2023). "Despite accumulating evidence linking elevated HBP flux to insulin resistance/diabetes, the underlying mechanisms remain poorly understood." (PMID 37107691, 2023). "In patients with type 1 diabetes (T1DM), as well as in those with type 2 diabetes (T2DM) on multiple daily insulin injections (MDIs), good glycemic regulation is imperative to reduce the risk of acute and chronic complications of diabetes." (PMID 38003943, 2023). "PLWH with at-risk alcohol use are more likely to meet criteria for prediabetes/diabetes and this is associated with impaired whole-body glucose-insulin dynamics." (PMID 37296413, 2023). "Due to deficiencies in insulin secretion and its action, diabetics cannot effectively metabolize glucose, and curcumin can have a therapeutic effect by playing a crucial role in β-cell functions." (PMID 37241737, 2023). "Type 1 diabetes mellitus is a metabolic disease always caused by the autoimmune destruction of pancreatic beta cells, leading to a complete deficiency in insulin secretion." (PMID 37584373, 2023). "Among the most common chronic diseases globally is diabetes mellitus (DM), defined by hyperglycemia caused by inadequate insulin production and/or reduced insulin action." (PMID 38133142, 2023). "In the context of diabetes, particularly T2D, hyperglycemia is triggered by defective insulin signaling, which causes insulin resistance and reduced glucose uptake by insulin-sensitive tissues." (PMID 37849988, 2023). "Diabetes is a kind of disease that occurs when blood glucose levels are high and is caused by insufficient insulin secretion or impaired insulin action." (PMID 36985444, 2023). "Diabetes is a multisystem disease that results from deficiencies in insulin secretion and insulin resistance." (PMID 37049602, 2023). "T1DM (5–10% of all diabetes) is caused by the cellular-mediated autoimmune destruction of insulin-producing pancreatic β-cells, resulting in insulin insufficiency." (PMID 37894680, 2023). "Chronic hyperglycemia caused by abnormalities in insulin secretion, insulin action, or both characterizes the group of metabolic illnesses known as diabetes mellitus." (PMID 37074460, 2023). "Type 2 diabetes mellitus (T2DM) is a chronic metabolic disorder caused by the pancreas' failure to secrete sufficient insulin or the body's inability to properly use the insulin it produces." (PMID 38179344, 2023). "We found that an appropriate distribution of food intake throughout the day permits a reduction in the insulin dose required to maintain glycemia within the range recommended by the American Diabetes Association for patients with T2DM of a range of severities." (PMID 37089422, 2023). "Further, since pre-diabetes is associated with impaired insulin secretion and/or insulin resistance we also included HOMA-IR in the analysis and found that an increase in IR was also associated with increased EATV and decreased EATA." (PMID 36709226, 2023). "Diabetes mellitus (DM) is a very serious disease of sugar metabolism, which can be caused by insufficient insulin production." (PMID 37893225, 2023). "Insulin manipulation or omission is a diabetes specific weight loss technique that is uniquely applicable to patients with type 1 diabetes." (PMID 36754894, 2023).
diabetes (continued). "In the case of glucose metabolism, for example, researchers have found that LPS can cause or exacerbate diabetes by interfering with signaling pathways that impede insulin-related signaling, leading to a decrease in the body’s sensitivity to insulin." (PMID 36986268, 2023). "For instance, antiviral innate immune signaling can deteriorate insulin secretion and insulin signaling and can cause childhood obesity and diabetes through yet largely unexplored mechanisms." (PMID 37830559, 2023). "Insulin use was associated with a lower risk of developing trochanteric bursitis in patients with diabetes." (PMID 37834819, 2023). "Adhering to MedDiet Also means promoting better-controlled blood glucose balance in terms of fasting blood glucose, HbA1c, insulin resistance, and risk of developing diabetes, as we found from the cluster of systematic reviews found about this health outcome." (PMID 37885010, 2023). "When diabetes causes insulin resistance, a large amount of insulin is required (hyperinsulinemia); therefore, a large number of insulin-degrading enzymes are used." (PMID 37511915, 2023). "It has been demonstrated that C‐peptide is associated with duration of diabetes, age of diagnosis, the need for insulin therapy, predicting glycaemic control, pro‐inflammatory condition, and microvascular and macrovascular complications." (PMID 36808709, 2023). "Obesity and elevated blood free fatty acid (FFA) levels lead to impaired insulin action causing insulin resistance in skeletal muscle, and contributing to the development of type 2 diabetes mellitus (T2DM)." (PMID 36982168, 2023). "High-GI carbohydrates diets have been shown to be risk factors for diabetes onset, while low-GI carbohydrates diets contribute to weight loss and improving insulin action and glucose tolerance in obese insulin-resistant individuals." (PMID 36839210, 2023). "For example, previous studies using similar rest–activity parameters showed that characteristics of a weakened rhythm were associated with higher fasting insulin and insulin resistance and higher odds of diabetes." (PMID 37987396, 2023). "Secondly, complex causes are impaired insulin secretion, worsening glucose disposal, pre-existing undiagnosed diabetes, or changes in metabolic and inflammatory homeostasis modification." (PMID 37867496, 2023). "Improved insulin sensitivity can help mitigate hyperinsulinemia and its associated risks, such as diabetes and cardiovascular complications." (PMID 38106751, 2023). "Adhesives attaching glucose sensors and continuous insulin infusion sets to the skin are proven to cause both allergic contact dermatitis and irritant contact dermatitis in patients with diabetes mellitus." (PMID 37445875, 2023). "Diabetes is associated with adverse changes in lipid profile, plasma insulin levels, blood glucose levels and also an increase in oxidative stress indices." (PMID 37151681, 2023). "The bioactive compounds in cherries prevent the risk of diabetes by increasing insulin secretion and metabolism." (PMID 37763199, 2023). "Timely initiation of exogenous insulin supplementation therapy is a necessary hypoglycemic management strategy." (PMID 37077814, 2023). "Summary of baseline factors associated with insulin sensitivity and glycaemic control (all models were adjusted for sex, age, Tanner stage and duration of diabetes)." (PMID 37715520, 2023). "Some mutations in the INS can lead to specific subtypes of diabetes, such as maturity onset diabetes of the young (MODY) or neonatal diabetes." (PMID 37888112, 2023). "Diabetes mellitus (DM) is a group of metabolic diseases caused by absolute or relative deficiency of insulin secretion and characterized by chronic hyperglycemia." (PMID 36843948, 2023). "Risk factors for obesity in this group are longer diabetes duration, higher insulin dose, pump treatment, experiencing frequent severe hypoglycemia, and low HbA1c." (PMID 36935526, 2023).
diabetes (continued). "After treatment with fenugreek powder in a prediabetic population, the development of diabetes was definitely related to serum insulin and negatively associated with HOMA-IR." (PMID 38099180, 2023). "Diabetes mellitus is a hyperglycemic condition caused by a decrease in insulin resistance, insulin secretion, or both." (PMID 36677754, 2023). "Diabetes mellitus (DM) is a metabolic disorder featured by hyperglycemia as a result of deficiency in insulin secretion and/or insulin action (Rayburn, 1997/9)." (PMID 37051594, 2023). "Diabetes mellitus is a syndrome and an endocrine disorder, primarily considered as a loss of glucose homeostasis because of the insulin action and/or secretion or both." (PMID 37193696, 2023). "Diabetes is a long-term illness caused by pancreatic dysfunction, which manifests as either inadequate insulin production or improper insulin utilization by the body." (PMID 36991714, 2023). "Diabetes mellitus (DM) is a group of disorders of carbohydrate, protein and fat metabolism caused by absolute or relative insufficiency of insulin secretion and/or dysfunction of insulin utilization." (PMID 37501096, 2023). "BUN was considered as a kidney function marker; a high level of urea increases insulin resistance and suppresses insulin secretion, which is associated with an increased risk of incident diabetes mellitus." (PMID 36909340, 2023). "Insulin resistance, the abnormal response of the body’s tissues to insulin, is one of the main causes of diabetes mellitus, which is one of the most prevalent metabolic diseases in the world." (PMID 37367903, 2023). "Higher insulin levels, reflecting lower sensitivity, are associated with greater age-related cognitive decline, and Alzheimer’s disease and type 2 diabetes mellitus share numerous mechanistic pathways." (PMID 37892346, 2023). "By using a significant risk increase of 20% (HR of at least 1.2) as a threshold, the 4 following risk factors were defined: BMI <25 kg/m2, diabetes duration ≥15 years, insulin treatment the past year, and low level of physical activity." (PMID 36701363, 2023). "These indicators include fasting blood glucose (FBG) levels, insulin use, and the presence of diabetes-related complications, such as ocular problems caused by diabetes." (PMID 38269284, 2023). "Diabetes-related knowledge, family support, fear of hypoglycemia, socioeconomic status, and insulin delivery devices have all been implicated as contributors to non-adherence." (PMID 38047210, 2023). "Diabetes is a metabolic disease caused by insulin insensitivity, insulin deficiency, and impaired biological function due to genetic and environmental factors." (PMID 37138277, 2023). "And subjects with elevated FFAs are at a higher risk of developing diabetes due to impaired insulin sensitivity." (PMID 37789017, 2023). "Our previous work demonstrated that most individuals with type 1 diabetes or children at risk of diabetes have autoantibodies to oxidative post-translationally modified insulin (oxPTM-INS)." (PMID 36207582, 2023). "Type 1 diabetes mellitus (T1DM) is due to certain factors mediating autoimmune destruction of the pancreas, resulting in insufficient insulin secretion, while type 2 diabetes mellitus (T2DM) is mainly caused by impaired islet function and IR." (PMID 37360526, 2023). "Diabetes is a chronic disease caused either by insufficient insulin production by the pancreas or inefficient insulin use by the body." (PMID 37372968, 2023). "Especially, mothers with first or first- and second-degree relatives with diabetes had an unfavourable risk profile with higher BMI and impaired insulin sensitivity." (PMID 36508047, 2023). "Diabetes mellitus (DM) is a metabolic disorder that is becoming more prevalent, marked by chronic hyperglycemia and a deficiency in insulin production or sensitivity." (PMID 38074157, 2023).
diabetes (continued). "Diabetes mellitus is a metabolic syndrome characterized by hyperglycemia caused by a defect in insulin secretion, decreased insulin action or both." (PMID 36814562, 2023). "Although the main risk factors for the development of diabetes are still under investigation, muscle mass is the main tissue that contributes to insulin-mediated glucose disposal, so its decrease contributes to insulin resistance." (PMID 37513585, 2023). "Diabetes is caused by the inability of electrically coupled, functionally heterogeneous β-cells within the pancreatic islet to provide adequate insulin secretion." (PMID 38018905, 2023). "2-AAA was originally discovered as a predictor of diabetes, and is associated with increased insulin secretion in animal models and cells." (PMID 37745703, 2023). "Increased hepatic fat accumulation is associated with decreased insulin clearance and sensitivity in type 2 diabetes mellitus patients." (PMID 37249651, 2023). "Diabetes mellitus is a state of hyperglycemia or high glucose levels caused by the inability of the body to produce insulin, insulin resistance, or both." (PMID 37372155, 2023). "Our data strengthen the finding that maternal BMI is independently associated with insulin levels since our study excluded women with diabetes before or during pregnancy." (PMID 36986206, 2023). "Fifth, another interesting finding is that Thiamine (vit B1) and Gabapentin are usually associated with the prescription of Insulin which is a sign of more advanced stages of diabetes." (PMID 37864248, 2023). "Over the past years, SOCS3 has been associated with glucose metabolism and diabetes progression, given that it is a crucial negative regulator of insulin signaling." (PMID 36896239, 2023). "Monogenic mutations are causative in about 1–2% of diabetes cases, and mutations in the INS gene are common." (PMID 36830724, 2023). "Aging has been linked to diabetes through several mechanisms, including age-associated insulin resistance and age-dependent disruption of insulin production." (PMID 36777336, 2023). "Aberrant insulin signaling is most prominent in diabetes and associated metabolic diseases (e.g., diabetes and obesity)." (PMID 36942499, 2023). "TXNIP is linked to oxidative stress; TXNIP methylation in blood is associated with future T2D27, and we found lower TXNIP methylation in the severe insulin-deficient diabetes subgroup of T2D50." (PMID 38086799, 2023). "Diabetes, in addition to impairing insulin signaling, has been linked to an increase in cerebrovascular inflammation and amyloid peptide (A) deposition." (PMID 38002034, 2023). "TBT exposure poses a high risk for the development of type 2 diabetes mellitus in mice because it produces insulin resistance, alters hepatic glucose metabolism, increases insulin levels, and decreases serum glucagon levels." (PMID 36875280, 2023). "Diabetes mellitus (DM) is a chronic and progressive condition defined by hyperglycemia caused by abnormalities in insulin production, insulin receptor sensitivity, or both." (PMID 36890575, 2023). "Diabetes, a multisystemic disorder, is caused by absolute or relative insulin deficiency or peripheral tissue resistance to insulin." (PMID 38206747, 2023). "A reduction in melatonin also can increase the risk of the development of type 2 diabetes mellitus by impairing insulin sensitivity and glucose tolerance." (PMID 36959654, 2023). "Diabetes mellitus, a group of metabolic disorders characterized by high levels of blood glucose caused by insulin defect or impairment, is a major risk factor for cardiovascular diseases and related mortality." (PMID 37226245, 2023). "Diabetes mellitus, as one of the main causes of death and disability globally, occurs when the pancreas cannot produce sufficient insulin or hyperglycemia is caused by insulin resistance." (PMID 38223574, 2023).
diabetes (continued). "Diabetes, caused by a long-term combination of genetic and environmental factors, is mainly due to insulin deficiency or insufficient insulin secretion, leading to function disorders in glucose, lipid and protein metabolism." (PMID 37732125, 2023). "Diabetes mellitus is a metabolic disorder caused by insufficient insulin secretion and insulin antagonism, characterized by persistent hyperglycemia, which eventually leads to specific complications." (PMID 37324866, 2023). "The cognitive burden associated with self-management of diabetes therapy drives preferences for advanced insulin delivery systems." (PMID 36828942, 2023). "The strong association between insulin treatment and weight gain leads to difficulty in managing diabetes in these patients." (PMID 38111445, 2023). "Insulin injections are the most common treatments for diabetes, but the pain and discomfort caused by intravenous injections induce the physical and mental inconvenience for diabetic patients." (PMID 37223469, 2023). "The increase in physical activity would increase the energy expenditure and promote insulin sensitivity, which in turn reduces the diabetes risk." (PMID 37674682, 2023). "In the general population and patients with diabetes, sleep deprivation, fragmentation, and decreased deep sleep are associated with decreased insulin sensitivity, possibly mediated by increased cortisol and Growth hormone (GH) levels." (PMID 36896174, 2023). "It was shown that in T1D, insulin and its precursor, preproinsulin, are major self-antigens targeted by T cells, and it was reported that patients with diabetes carrying the PTPN22R620W genetic variant showed higher levels of insulin autoantibodies (IAAs)." (PMID 38203514, 2023). "Disordered eating behaviours, such as insulin omission, are associated with an increased risk of diabetes mellitus-related complications and mortality." (PMID 37259043, 2023). "The mitochondria have been found to be major regulators of the secretion of insulin, and mutations in mtDNA are directly involved in the development of type 2 diabetes mellitus." (PMID 37109219, 2023). "Drugs used for the treatment of diabetes include oral hypoglycemic agents and insulin; however, these drugs have been reported to cause many side effects related to the gastrointestinal system." (PMID 37754257, 2023). "Diabetes is classified into type 1 diabetes, which is caused by a decrease in insulin secretion due to a reduction in β cells in the pancreas, and type 2 diabetes, which is caused by a reduction in insulin secretion and IR." (PMID 37754257, 2023). "Subsequently, however, with the loss of the insulin reserve, the individual reaches the stage of full-blown diabetes and, therefore, a greater risk of organ damage." (PMID 37373556, 2023). "The destruction of pancreatic beta cells leads to the development of T1DM, and this type of diabetes often leads to an absolute deficiency of insulin." (PMID 38169604, 2023). "Type 2 diabetes mellitus (T2DM) is a chronic endocrine metabolic disease caused mostly by insulin dysfunction." (PMID 37293508, 2023). "Regarding emotional status, more years of suffering from diabetes, treatment with insulin and the hours being idle per day were associated with an increased burden of anxiety." (PMID 37998065, 2023). "Cholesterol accumulation in the transgenic model of in vivo activation of SREBP2 resulted in reduced β-cell mass and insulin-deficient diabetes." (PMID 36830593, 2023). "A metabolic illness that causes hyperglycemia due to inadequate insulin production, diabetes is a complex chronic disease." (PMID 37232930, 2023). "This study showed that indeed mean diabetes-associated costs are substantially higher for patients that use insulin pumps or rtCGM devices." (PMID 37029362, 2023). "Another research established a link between statin use and an increased risk of developing diabetes, as well as reduced insulin sensitivity and secretion." (PMID 37139700, 2023).